FOXO3 (forkhead box O3)
Diseases named in the same sentence as FOXO3 in open-access papers (continued):
Sharing a sentence is not in itself a finding about the gene and the disease.
osteoarthritis (13 papers, 2019 to 2025). A noninflammatory degenerative joint disease occurring chiefly in older persons, characterized by degeneration of the articular cartilage, hypertrophy of bone at the margins and changes in the synovial membrane. "Previous studies have shown that FOXO1 and FOXO3 phosphorylation within cartilage leads to cell death and osteoarthritis due to the loss of autophagy genes that are known to protect chondrocytes from stress and are under the control of FOXO3." (PMID 30678074, 2019). "Additionally, early-onset osteoarthritis was observed in FoxO1 or FoxO3-deficient mice, whereas FoxO1 shielded chondrocytes from oxidative stress and promoted the overexpression of genes related to autophagy and proteoglycan 4, a crucial joint lubricant." (PMID 38987770, 2024). "An IL-1β-induced osteoarthritis chondrocyte model was created to study the therapeutic effects of FoxO3-NETT@SMs on osteoarthritis chondrocytes." (PMID 40041910, 2025). "FoxO3-NETT@SMs targeting-regulated Foxo3 gene in vivo to modulate mitophagy for osteoarthritis therapy." (PMID 40041910, 2025). "A study demonstrated that CircFOXO3 exerts protective effects against osteoarthritis (OA) by targeting its parental gene, FOXO3, and promoting PI3K/AKT-mediated autophagy." (PMID 38962732, 2024). "In an in vivo model of osteoarthritis (OA), the upregulation of ferroptosis, regulated by Forkhead box O3 (FOXO3) via the NF-κB/MAPK signaling pathway, accelerates the progression of OA." (PMID 39769377, 2024). "For example, circBUB1B_544aa and the host gene BUB1B act synergistically to exacerbate multiple myeloma, circFOXO3 negatively regulates the host gene FOXO3 in osteoarthritis through activation of autophagy." (PMID 38150467, 2023). "In view of the importance of synovial cells in OA pathogenesis, we explored the interaction and cross-talk between TGF-β1 and FOXO3 in human osteoarthritis synovial fibroblasts (OASFs)." (PMID 31232696, 2019). "This study explored the interaction and cross-talk of TGF-β1 and FOXO3 in human osteoarthritis synovial fibroblasts (OASFs)." (PMID 31232696, 2019).
asthma (12 papers, 2015 to 2025). "In three different studies we have reported significant association between many SNPS in ADAM33, GMBS, and FOXO3 genes for asthma and AR." (PMID 32295284, 2020). "Previous studies have demonstrated single nucleotide polymorphisms in FOXO3 in peripheral blood of asthma patients, and the expression of FOXO3 decreased significantly in the lungs of smokers or COPD patients." (PMID 33298101, 2020). "Previous studies have shown the association between single nucleotide polymorphism in the FOXO3 gene and asthma." (PMID 30696075, 2019). "The objective of this study is to assess the association of rs13217795, an intronic FOXO3 single-nucleotide polymorphism, with asthma and allergic rhinitis." (PMID 29141605, 2017). "In this study, we explored the association between an intronic single-nucleotide variant in FOXO3 (rs13217795) and two disease phenotypes—asthma and allergic rhinitis." (PMID 29141605, 2017). "Recently, a novel association between the FOXO3 single-nucleotide polymorphism rs13217795 and asthma susceptibility was described." (PMID 29141605, 2017). "Interestingly, one of the vitamin C DMCs previously associated with atopy in nasal cells (cg26575105; upstream of FOXO3) has also been associated with asthma in airway epithelial cells and with fractional exhaled nitric oxide in a separate nasal cell EWAS." (PMID 38413986, 2024). "Nevertheless, based on the current knowledge, we believed that dysregulated miR-10a-5p-FOXO3 and miR-146a-5p-FOXO3 in bronchial epithelial cells might be one of the important pathobiological mechanisms underlying both asthma and COPD." (PMID 30696075, 2019). "The aberrant regulations of miR-10a-5p-FOXO3 and miR-146a-5p-FOXO3 in bronchial epithelial cells might be important mechanisms underlying both asthma and COPD." (PMID 30696075, 2019). "Thus, the association of FOXO3 (rs13217795) with asthma and allergic rhinitis is highly plausible from a biologic standpoint." (PMID 29141605, 2017). "Interestingly, another research shows that the FOXO3 is a gene involved in the etiology of a number of respiratory diseases, and it is proved to be associated with asthma and allergic rhinitis, which is consistent with our research results that FOXO3 is an important hub gene of AIT for AR." (PMID 37430199, 2023). "Expression of hsa-miR-148b-3p and hsa-miR-221-5p correlated with FEV1/FVC (%) and these altered miRNAs act in key signaling pathways for asthma disease and the regulated expression of some genes (FOXO3, PTEN, and MAPK3) involved in these pathways." (PMID 36675122, 2023). "In a mouse model of asthma, EZH2 promoted asthma development through the FOXO3-miR-34b-BTG2 axis." (PMID 39108751, 2024). "The polymorphism of transcription factor FOXO3 was confirmed to regulate the overactivation of mast cells, downregulation of anti-inflammatory factors, and production of cytokines during the pathogenesis of COPD and asthma." (PMID 34136532, 2021). "Following further biologic elucidation of the role of FOXO3 in asthma and allergic rhinitis, these phytochemicals may represent attractive therapeutic alternatives." (PMID 29141605, 2017). "As TGFRB1, FOXO3, and PTEN are target genes of hsa-miR-148b-3p, and MAPK3 is the objective gene of hsa-miR-221-5p, all are involved in the signaling pathways related to asthma disease." (PMID 36675122, 2023).
asthma (continued). "The expression of hub genes other than FOXO3 was decreased in the GSE147878, suggesting that hub genes other than FOXO3 might be key genes in the regulation of severe asthma." (PMID 35645813, 2022). "Hub genes in the black module except FOXO3 were down-regulated in the GSE143303, which showed hub genes other than FOXO3 might be involved in severe asthma but not particularly regulate severe eosinophilic asthma." (PMID 35645813, 2022).
diabetic nephropathy (12 papers, 2014 to 2025). "Based on the results of transcriptomics, the pathogenesis of diabetic kidney disease may involve 11 candidate differential genes: Egr1, Foxo3, Pik3r3, Fgf1, Sost, Wnt10a, Tgif2, Akt2, Mep1b, Col1a1, Apoe." (PMID 36249745, 2022).
emphysema (12 papers, 2012 to 2025). "A recent study has shown that SIRT1 deficiency increases FOXO3 acetylation and exacerbates emphysema in CSE-induced mouse models, while activation of SIRT1 reduces FOXO3 acetylation and improves lung functions." (PMID 35313881, 2022). "FOXO3 deficiency has been confirmed to play an important role in regulating lung inflammation of COPD/emphysema, which has emerged as a new approach to address the development of pulmonary inflammatory diseases." (PMID 34136532, 2021). "These evidences support the hypothesis about the role of deficiency of FoxO3 in development of COPD/emphysema." (PMID 28105251, 2016). "Yao H., Chung S., Hwang J.W., Rajendrasozhan S., Sundar I.K.,Dean D.A., McBurney M.W., Guarente L., Gu W., Rönty M., KinnulaV.L., Rahman I. SIRT1 protects against emphysema via FOXO3-mediated reduction of premature senescence in mice." (PMID 41164273, 2025). "Jiang H., Xu Y., Jiang Y., Li Y. FOXO3 activation prevents cellular senescencein emphysema induced by cigarette smoke." (PMID 41164273, 2025). "The activation of the antiageing SIRT1 1/FOXO3 pathway seems to protect against emphysema through FOXO3-mediated reduction of cellular senescence in emphysematous mice." (PMID 37509711, 2023). "SIRT1 protected against emphysema via FOXO3-mediated reduction of premature senescence and apoptosis in mice." (PMID 31881011, 2019). "Specifically, the anti-aging SIRT1, that is reduced in lungs of COPD patients, seems to protect against emphysema through FOXO3 (Forkhead box O3)-mediated reduction of cellular senescence, independently of inflammation." (PMID 23222732, 2012). "SIRT1 protects against emphysema through FOXO3-mediated reduction of cellular senescence." (PMID 32051395, 2020). "Moreover, genetic ablation of FoxO3 led to pulmonary emphysema and exaggerated inflammatory response in lungs of mice exposed to CS." (PMID 28105251, 2016).
lung adenocarcinoma (12 papers, 2011 to 2024). A carcinoma that arises from the lung and is characterized by the presence of malignant glandular epithelial cells. "Consistently, FOXO3 expression was depleted in human lung adenocarcinoma, and its activation upregulated level of caspase‐dependent apoptosis in lung adenocarcinoma cells exposed to this DNA‐damaging carcinogen." (PMID 33655712, 2021).
acute lymphoblastic leukemia (11 papers, 2012 to 2024). Leukemia with an acute onset, characterized by the presence of lymphoblasts in the bone marrow and the peripheral blood. "Characterisation of a common chromosomal 6q21 deletion in mature B cell lymphomas and childhood acute lymphoblastic leukaemia has also uncovered FOXO3 as being one of the three tumour suppressor genes frequently deleted in these rare blood cancers." (PMID 32372224, 2020). "In agreement with our findings, FOXO3 acetylation has been shown to mediate the antiproliferative functions of glucocorticoid in B acute lymphoblastic leukemia (B-ALL)." (PMID 31357743, 2019). "FOXO3 is an indirect target of BMS-345541 (a highly selective IKK inhibitor) in T-cell acute lymphoblastic leukemia (T-ALL) in which the expression of p21Cip1 is up-regulation by increased nuclear translocation of FOXO3a after treatment with BMS-345541." (PMID 30045773, 2018). "Therapy-resistant acute lymphoblastic leukemia (ALL) cells were shown to inactivate Foxo3 activity to escape apoptosis induction." (PMID 26098777, 2015). "We found that cells from prednisone-resistant T-acute lymphoblastic leukemia (T-ALL) patients showed cytoplasmic localization of FOXO3 in comparison to prednisone-sensitive patients suggesting its inactivation." (PMID 23828551, 2013).
liver fibrosis (11 papers, 2016 to 2025). "Turmeric can inhibit the development of lung and liver fibrosis via its antioxidant and anti-inflammatory properties through reducing various inflammatory mediators as FOXO-3, TGF-β, TNF-α, and MCP1 in the lung and liver." (PMID 36301384, 2022). "It is reported that reactivation of FOXO3 can protect against hepatic fibrosis through attenuating cell proliferation and transdifferentiation of hepatic stellate cells." (PMID 35222075, 2022).
muscle atrophy (11 papers, 2013 to 2025). The loss of muscle tissue due to inactivity or disease. "Muscle atrophy has been also linked to the forkhead box O3 (Foxo-3) transcription factor and its overexpression in skeletal muscle was sufficient to induce dramatic skeletal muscle wasting." (PMID 26668061, 2015). "On the other hand, phosphorylated Akt inhibits protein degradation through inhibition of Muscle RING finger 1 (MuRF1) and muscle atrophy F-box (MAFbx/Atrogin-1), which are muscle-specific E3 ubiquitin ligases mediated by forkhead box O3a (FoxO3a)." (PMID 36297085, 2022). "In denervation-induced muscle atrophy, Fbxo32 mRNA level rises acutely after denervation, but returns to basal levels by day 14 despite persistent increase in FoxO3 activity." (PMID 28170423, 2017).
thyroid cancer (11 papers, 2011 to 2025). "In the present study, we also showed that CDDP induced thyroid cancer cells death via FOXO3 increment." (PMID 29299162, 2017). "The negative regulators of the cell cycle, p21 and p27, are strongly induced by transcriptional activation of FoxO3 in BRAFV600E positive thyroid cancer cells." (PMID 21249150, 2011). "FOXO3 plays a tumor-suppressor role in differentiated thyroid cancers where its expression is downregulated; notably, FOXOs seem to promote the antitumor immune response by negatively regulating several immunosuppressive factors (e.g., PD-L1 and VEGF) and positively regulating chemokine attractants." (PMID 35625697, 2022). "Although more detailed experiments are necessary to elucidate the underlying expression profiling between FOXO3 and MUL1 in tissues of thyroid cancer patients, we could speculate that while p-AKT is increased, FOXO3 and MUL1 is decreased." (PMID 29299162, 2017). "Several molecular mechanisms which are possibly regulated by BRAFV600E may control FoxO3 activity in thyroid cancer." (PMID 21249150, 2011). "Thus, FOXO3 could be a good therapeutic target for thyroid cancer therapy through induction of the MUL1-AKT axis." (PMID 29299162, 2017). "In summary, SNHG5 is universally underexpressed in thyroid cancer and exerts tumor-suppressive effects through the RBM47/USP21/FOXO3 pathway and miR-510-5p-related mechanisms." (PMID 41234719, 2025). "FOXO3 was determined as a putative regulator of MUL1, therefore FOXO3 and MUL1 were suppressed in thyroid cancer cells." (PMID 29299162, 2017). "The ectopic expression of PAX3 dramatically inhibited thyroid cancer progression in vitro and in vivo through inhibiting the activity of PI3K/Akt and MAPK signaling pathways and promoting the expression and activity of transcription factor FOXO3." (PMID 33817318, 2021). "In thyroid cancer cells, a chemopreventive non-steroidal anti-inflammatory drug, sulindac sulfide, blocks the PI3K-AKT pathway and leads to the activation of FOXO3, which increases the expression of Bim, GADD45A and p27KIP1 to promote cell cycle arrest and apoptosis." (PMID 29299162, 2017).
acute kidney injury (10 papers, 2020 to 2026). Sudden and sustained deterioration of the kidney function characterized by decreased glomerular filtration rate, increased serum creatinine or oliguria. "Although, hypoxia-induced FOXO3 activation leads to tubular regeneration in acute kidney injury, the constitutive activation of FOXO3 in kidney tubular cells may cause growth arrest and apoptosis." (PMID 33795838, 2021). "Overall, the current study demonstrated that RA plays a notable role in improving inflammation and apoptosis in folic acid-induced renal failure, which can result from its involvement in the FoxO3/NF-κB signaling pathway." (PMID 39906624, 2025). "In this regard, it has been shown that the conditional deletion of FOXO3 exacerbates acute kidney injury (AKI) to CKD transition by reducing epithelial autophagy and lowering SOD2 expression." (PMID 34291592, 2021).
Arthritis (10 papers, 2013 to 2026). Inflammation of a joint. "Using clinical, serologic, and biochemical methods, the arthritis that developed in mice carrying a loss‐of‐function mutation in Foxo3 was compared with that which occurred in littermate controls." (PMID 27214848, 2016). "Loss of Foxo3 function resulted in more severe arthritis in vivo (both clinically and histologically) and was associated with higher titers of anticollagen antibodies and interleukin‐6 in the blood." (PMID 27214848, 2016). "We next wished to determine if loss of FOXO3 in myeloid cells alone offers protection from K/BxN-serum transfer arthritis." (PMID 25969990, 2015). "We found that carriage of the Foxo3‐null allele was associated with more‐severe arthritis." (PMID 27214848, 2016). "Thus we investigated myelopoiesis, neutrophil accumulation during peritoneal inflammation, and susceptibility to K/BxN-serum transfer-induced arthritis in a single strain of C57BL/6-congenic Foxo3 null mice." (PMID 25969990, 2015). "Collagen‐induced arthritis, the most commonly used mouse model of RA, was used to assess how Foxo3 contributes to arthritis severity." (PMID 27214848, 2016). "These defects appear to be at least partially intrinsic to the myeloid lineage, as deleting Foxo3 specifically from myeloid cells using LysMCre also leads to an elevated number of neutrophils and protection from K/BxN-serum transfer-induced arthritis." (PMID 25969990, 2015). "To do this, we first investigated whether a role of FOXO3 in altering arthritis severity was biologically plausible by examining the contribution of FOXO3 to the severity of immune‐mediated arthritis in vivo." (PMID 27214848, 2016). "Among the targets that are down-regulated during collagen immunization of the DBA-2/J strain, we found Rorc, which is involved in Th17 differentiation, and Foxo3, which is involved in cell cycle and survival, both of which are directly related to arthritis pathogenesis." (PMID 23359619, 2013). "Thus, FOXO3 has been suggested as a target for arthritis therapy." (PMID 25969990, 2015). "Foxo3 can inhibit the activation of NF-kB and block NF-κB/MAPK signal transduction to prevent ferroptosis, which may alleviate the symptoms of arthritis." (PMID 38891634, 2024). "We sought to clarify the contribution of FOXO3 to prognosis in RA by combining detailed analysis of nonradiographic disease severity measures with an in vivo model of arthritis." (PMID 27214848, 2016). "As has been previously suggested, these phenotypes are at least partially myeloid lineage-intrinsic, as mice lacking Foxo3 specifically in myeloid cells, also, have an elevated number of neutrophils in the spleen and are protected from K/BxN-serum transfer arthritis." (PMID 25969990, 2015).
autoimmune disease (10 papers, 2018 to 2025). A disorder resulting from loss of function or tissue destruction of an organ or multiple organs, arising from humoral or cellular immune responses of the individual to their own tissue constituents. "FOXO3 has extensive connection with some autoimmune diseases." (PMID 38505423, 2024). "Similarly, Forkhead Box O3 (FOXO3a) is regarded as a regulator in autoimmune disorders." (PMID 37834287, 2023).
pancreatic ductal adenocarcinoma (10 papers, 2015 to 2025). An infiltrating adenocarcinoma that arises from the epithelial cells of the pancreas. "For example, FOXO3 is essential for maintenance of CSC properties in pancreatic ductal adenocarcinoma; FOXO4 is related to stem cell-like properties of large B-cell lymphoma cells." (PMID 29723215, 2018).